CD244 (CD244 molecule)
Diseases named in the same sentence as CD244 in open-access papers (continued):
Sharing a sentence is not in itself a finding about the gene and the disease.
tumor (continued). "With respect to the myeloid tumor compartment, it is theorized that CD244 signaling augments the immune-suppressive characteristics of both DCs and MDSCs." (PMID 37835502, 2023). "Within HNSCC patients and their mouse model counterparts, there is a marked increase in CD244 levels in tumor-infiltrating CD8+ T cells, which also correlates with heightened PD-1 expression." (PMID 37835502, 2023). "This hints at a potential weakening of the immune response within the tumor environment by CD244 signaling." (PMID 37835502, 2023). "CD244 (2B4) binding to the ligand CD48 has been found to be a signaling pathway for co-stimulation or negative regulation of multiple immune cells in tumor, that currently considered to be an important marker of immune cell senescence." (PMID 38035110, 2023). "The results demonstrated that different tumor antigens influenced the distribution of T cell subsets, with the depletion phenotype PD-1 and cell senescence phenotype CD244 overexpressed in CD8+T cell subsets." (PMID 38035110, 2023). "The infiltrating edge of GBM, relative to tumor in total, was enriched with RNAs for stimulators of NK cytotoxicity (i.e., CD244, the fractalkine receptor for immune cells); chemokines for thymocytes and DCs; and immune stimulatory IL-12 receptors." (PMID 35316217, 2022). "CTLA4, HAVCR2, PVRL2, PDCD1, SIGLEC15, TIGIT, and VTCN1 expression levels were higher in tumor tissues, while CD244, LAG3, PDCD1LG2, and CD274 expression levels were found to be lower." (PMID 35923695, 2022). "When human NK cells were stimulated by anti-CD244 mAb, their cytotoxic ability against tumour cells significantly improved." (PMID 35806034, 2022). "Three of these proteins—IL 12, TNFSF14, and CD244—have previously been considered as useful for clinical application in cancer therapy as promoters of tumor cell apoptosis, or as therapeutic targets." (PMID 35682983, 2022). "Recent studies have linked the CD244 inhibitory signaling to maintaining an exhausted phenotype in NK- and T-cells in chronic infection (i.e., SARS-CoV-2) and cancer, leading to tumor growth." (PMID 34944879, 2021). "The effect of “pseudo-failure” of T cells with elevated CD244 expression on tumor outcome needs further examination." (PMID 33841431, 2021). "CD244 can also prevent NK cells from achieving anti-tumor immunity by regulating the function of DCs." (PMID 33841431, 2021). "Isolation of MDSCs from tumor-bearing mice showed differences in functional activity between CD244+ MDSCs and CD244− MDSCs, in that the former cells had significant inhibitory activity against CD8+ T cells." (PMID 33841431, 2021). "We next evaluated the expression of other immune checkpoints associated with T cell exhaustion (e.g. TIM3, CD160, CD244, and CD73), whose ligands are expressed on both myeloid and tumor cells." (PMID 33469002, 2021). "There is evidence that CD244 is primarily expressed by NK cells, T cells, MDSCs, and DCs in the tumor microenvironment and that it functions in the regulation of these cells." (PMID 33841431, 2021). "CD244 is on the surfaces of various immune cells in the tumor microenvironment, and it helps to regulate immune function, and plays an essential role in tumor onset and development." (PMID 33841431, 2021). "PD-1, TIM-3, CTLA-4, LAG-3, and CD244 mRNA levels were relatively similar amongst the different grades of tumor budding." (PMID 32393998, 2020). "Further studies are required to elucidate the CD244 signaling pathways in DCs and to determine the influences of the tumor microenvironment on those pathways." (PMID 30546369, 2018). "CD244 is a SLAM family receptor with activating and inhibitory signaling capacities implicated in the functions of NK cells, T cells, DCs and MDSCs in the tumor microenvironment." (PMID 30546369, 2018). "Recently, the expression of CD244 has been described on MDSCs in tumor-bearing mice, with 30–50% of Gr-MDSC expressing CD244 in four syngeneic tumor models." (PMID 30546369, 2018).
tumor (continued). "Consistent with a role in T-cell exhaustion, increased CD244 expression on antigen-specific CD8+ T cells from the spleens of tumor-bearing mice correlated with reduced IL-2 and IFN-γ production." (PMID 30546369, 2018). "All tumor isolates displayed CD244 in large amounts, and most expressed low to moderate levels of NK1.1." (PMID 28692033, 2017). "In contrast, deletion of CD244 in monocytes using Cre-Lox recombination in mice resulted in a higher infiltration of anti-tumor Ly6Clow macrophages, demonstrating an inhibitory role for CD244 in anti-tumor macrophage generation." (PMID 40756366, 2025). "Moreover, stimulation by CD48‐expressing tumor cells induces CD244 internalization on NK cells, reducing its surface expression and consequently impairing NK cell activation and cytotoxicity." (PMID 40959206, 2025). "Flow cytometry analysis confirmed that CD244 expression was higher in tumor-infiltrating mo-Mac from mice fed on indole-poor diet, suggesting that lack of dietary AhR ligands could favor a pro-tumorigenic phenotype in macrophages." (PMID 41331250, 2025). "Nevertheless, we cannot exclude the possibility that CD244 may modulate other myeloid cell types in a cis- or trans-manner to regulate the tumor microenvironment." (PMID 38424542, 2024). "However, the precise molecular mechanism and contribution of CD244 to tumor immunity in monocytes/macrophages remains elusive due to the co-existing lymphoid cells expressing CD244." (PMID 38424542, 2024). "Furthermore, NK cells expanded via the engagement of the SLAMF2/CD48-SLAMF4/CD244 axis showed stronger anti-tumor capability and infiltration ability into the tumor microenvironment, leading to an improvement in therapeutic efficiency." (PMID 38612827, 2024). "CD244 is involved in immune tolerance and regulation of tumor cells via T cell inhibition." (PMID 38633624, 2024). "OS and DFS relative to CD244 in 33 tumor types were assessed using GEPIA2." (PMID 38633624, 2024). "Furthermore, we compared the CD244 promoter methylation levels in distinct tumor types with those in corresponding normal tissues." (PMID 38633624, 2024). "CD244 plays a critical role in regulating immune responses such as NK cell-mediated cytotoxicity, leukocyte activation, cytokine production, and clearance of tumor cells." (PMID 38633624, 2024). "Next, we examined whether a specific deletion of CD244 on monocyte-lineage cells within tumors could reduce tumor growth." (PMID 38424542, 2024). "However, the expression levels of CD244 in tumor tissues were up-regulated in kidney renal papillary cell carcinoma (KIRC) and kidney renal papillary cell carcinoma (KIRP)." (PMID 38633624, 2024). "We analyzed tumor samples from CD244fl/fl and CD244fl/flLysMcre mice using flow cytometry and real-time quantitative PCR to confirm whether CD244 regulates the function of macrophages." (PMID 38424542, 2024). "However, monocytes and macrophages in the skin did not express CD244, while they significantly upregulated their CD244 expression after tumor inoculation." (PMID 38424542, 2024). "We firstly compared the differences of CD244 expression in various tumor and normal tissues." (PMID 38633624, 2024). "There is also evidence that using CD244 as the co-stimulation domain to construct CAR-NK cells for adoptive immunotherapy could significantly improve the anti-tumor activity of CAR-engineered cells." (PMID 33841431, 2021). "CD244 is a regulatory receptor present in various immune cells, and can therefore be regarded as an immune checkpoint that regulates the immune response and kills tumor cells." (PMID 33841431, 2021). "In addition, the importance of PD-1 and CTLA-4, TIM-3, CD160, and CD244 in promoting tumor growth and progression has been reported in preclinical models." (PMID 32393998, 2020).
tumor (continued). "The evidence that inhibitory CD244 signaling contributes to immunosuppression in the tumor microenvironment suggests that targeting CD244 could provide a strategy for overcoming resistance to existing checkpoint inhibitors by multiple mechanisms." (PMID 30546369, 2018). "Here, we discuss the role of CD244 in tumor-mediated immune cell regulation." (PMID 30546369, 2018). "The correlation between CD244 expression and immunosuppressive capacity in these tumor-associated MDSCs is consistent with the inhibitory role of CD244 signaling in NK cells and CD8+ T cells in the tumor microenvironment." (PMID 30546369, 2018). "Besides the effect on immune cells, recent evidence suggests a direct effect of CD244 signaling on CD244-expressing tumor cells." (PMID 30546369, 2018). "However, other cell surface markers of this tumor were identical to other EB tumors (B220lo/CD117+/CD25+/CD244+/sIg–)." (PMID 28692033, 2017). "Additionally, we observed increased Cd244 transcripts in tumor cells of EB mice alone, which correlates with increased cell surface display of CD244 observed in flow cytometric analyses." (PMID 28692033, 2017). "We mainly intended to determine whether the CD244 expression was relevant to tumor survival time." (PMID 38633624, 2024). "Expression of CD244 is linked to the generation of inhibitory molecules and the inhibition of antigen-specific CD8+T cell activity, primarily spreading inhibitory signals in immune cells linked with tumors and immunosuppression in tumor microenvironment experiences." (PMID 36911389, 2023). "The introduction of CD244 as a critical co-stimulant molecule on the surfaces of NK cells, as a second and third generation CAR structure, can significantly enhance the anti-tumor effect of CAR-NK cells and reduce the inactivation of CAR-engineered cells caused by some tumor cells." (PMID 33841431, 2021). "Among them, 2B4 (CD244) and CS1 (SLAMF7) are major NK cell receptors playing a significant role in anti-tumor immunity." (PMID 40852706, 2025). "Similar to the results obtained with CD244−/− mice, monocyte-specific deletion of CD244 in CD244fl/flLysMcre mice significantly reduced tumor growth compared to littermate control CD244fl/fl mice." (PMID 38424542, 2024). "We discovered a strong positive correlation of CD244 expression with immune infiltrations of neutrophils, dendritic cells, monocytes, B cells, and CD8+ T cells across many tumor types." (PMID 38633624, 2024). "Additionally, the results of intraperitoneal tumor clearance experiments indicate that EAT2-deficient mice boast a stronger ability to clear myeloma cells compared to wild-type (WT) mice, suggesting that the binding of CD244 with EAT-2 plays an immunosuppressive role." (PMID 39578914, 2024). "Our PPI network analysis identified key interactions between HLA-DRB5 and CD244, as well as HSD17B13 and CD244, as potential therapeutic targets in LUAD, with these genes showing downregulation in tumor tissues." (PMID 39092217, 2024). "CD244-/- mice showed impaired tumor growth of HNSCC, and anti-SLAMF4 treatment also impaired the growth of established HNSCC tumors while it increased CD8+ TIL infiltration, suggesting SLAMF4 plays an inhibitory role in the immune response to HNSCC." (PMID 38476238, 2024). "To explore the significance of the interaction of these receptors during interaction with tumor cells, we blocked either CD58 (on NALM-6 targets) or CD2/CD244 (on CAR T cells)." (PMID 35881486, 2022). "CD2 and CD244 are members of the CD2 family of proteins and interact with the partner proteins CD58 and CD48 either on other T cells (homotypic) or tumor cells (heterotypic)." (PMID 35881486, 2022). "Based on the findings of tumor growth studies in a murine model of HPV-driven HNSCC, CD244 has been suggested as a target for immunotherapy." (PMID 35682983, 2022).
tumor (continued). "We demonstrated that P4HA1 expression was positively correlated with the expression of TNFSF15, CD80, VTCN1, TNFSF18, and CD200R1 in multiple tumor types but negatively correlated with the expression of CD40LG and CD244." (PMID 35812752, 2022). "T cells have an essential role in tumor immunity, and CD244 is expressed by CD4+ and CD8+ T cells, thereby regulating the anti-tumor effect of these cells or mediating immune escape in mice." (PMID 33841431, 2021). "BTLA and HAVCR2 mediate the inhibition of human tumor specific CD8 + T cells, and CD244 mediates the dysfunction of natural killer cells." (PMID 34512623, 2021). "We found that mRNA levels of PD-1, TIM-3, CTLA-4, TIGIT, CD160, CD244, and KLRG1 were elevated in CRC tumor tissue, implicating their potential contribution to CRC development and/or progression." (PMID 32393998, 2020). "In syngeneic C57BL/6 mouse models of pancreatic adenocarcinoma and lung carcinoma, frequencies of T-cells exhibiting co-inhibitory receptors CD244, PD-1, and BTLA were increased in tumor-bearing mice compared with naïve controls." (PMID 30546369, 2018). "When all tumor samples were evaluated together the correlation of GZMH, ABL1, IL-7, LY9, IL-12, SCAMP3, and CD244 were highly significant (p < 1 × 10−6)." (PMID 29587383, 2018). "CD244, a signaling lymphocyte activation molecule (SLAM) family member, may confer tumor-protective effects." (PMID 40186663, 2025). "Secondly, considering the role of M1 macrophages in the development and progression of various tumor types, it is essential to determine if the anti-tumorigenic function of CD244-negative monocyte-lineage cells holds true for other tumor types as well." (PMID 38424542, 2024). "Tim-3, LAG3, BTLA and CD160 were expressed by a mean of <2% of tumor-infiltrating CD8 T cells, and while CD244 (2B4) was present on higher numbers of CD8 T cells in cSCC, the frequencies of CD244+CD8 T cells did not significantly differ between cSCC, NS and blood." (PMID 33479027, 2021). "However, experimental studies of CD244, NCR1, and NCR2 showed that knocking them down in NK cells affected tumor surveillance or metastasis (eTable 6 in the Supplement)." (PMID 31483464, 2019). "Taken together, these findings suggest that CD244 signaling on NK cells, CD8+ T cells, DCs, and MDSCs may contribute to immunosuppression in the tumor microenvironment." (PMID 30546369, 2018). "This exhaustion did not occur in CD244+ NK cells co-cultured with non-tumor liver-infiltrating monocyte/macrophages, which exhibited significantly lower expression of CD48 than those from tumor." (PMID 30546369, 2018). "Indeed, CD11b+Gr1+ cells were also positive for CD244 in livers of B16 and RIL175 tumor-bearing mice." (PMID 25401795, 2014). "To determine the impact of CD244 expression in tumor-infiltrating monocyte-lineage cells, we analyzed CD244 expression on monocytes and macrophages in the skin of C57BL/6 wild-type (WT) naïve mice and in tumor masses at 14 days following subcutaneous injection with 1 × 106 B16F10 tumor cells." (PMID 38424542, 2024). "There is also evidence that CD244 does not directly stimulate the proliferation and activation of tumor-specific T cells, but acts as a co-stimulus that enhances the antigen activation reaction of tumor-specific T cells by enhancing the T cell receptor signal." (PMID 33841431, 2021). "Moreover, alterations correlated with distant metastasis emereged with significantly increased expression in SAMRCD1 in low-ITK group, but CD244 and SOCS1 in high-ITK group (p < 0.001), which indicated as oncogene or tumor suppressors in numerous cancers and potential therapeutic targets." (PMID 34702300, 2021). "To confirm that CD11b+Gr-1+ cells represent MDSC rather than neutrophils in our tumor-bearing mice, we studied whether CD11b+Gr-1+ cells were also positive for CD244, which has been proposed as a marker to distinguish neutrophils from granulocytic MDSC." (PMID 25401795, 2014).
tumor (continued). "Furthermore, in MDSCs from tumor-bearing mice, CD244 expression correlates with suppression of antigen-specific CD8+ T cell function and production of suppressive molecules, suggesting a role for CD244 signaling in the immunosuppressive function of these cells." (PMID 30546369, 2018). "We quantified the basal migration of CAR T cells in the absence of tumor cells by TIMING and then quantified a posteriori the cell surface abundance of CD2 and CD244 by fluorescent immunostaining and microscopy." (PMID 35881486, 2022). "For instance, in murine NK cells, stimulation of 2B4 with an anti-CD244 mAb lead to increased IFN-γ production and increased non-MHC-restricted killing of tumor cells." (PMID 32630303, 2020).